FLI1 (Fli-1 proto-oncogene, ETS transcription factor)
Diseases named in the same sentence as FLI1 in open-access papers (continued):
Sharing a sentence is not in itself a finding about the gene and the disease.
tumor (continued). "Our results may remind physicians that they should be aware of the possibility of tumor recurrence and poor survival during the surveillance of specific subtypes of GC exhibiting FLI1 hypermethylation." (PMID 31675985, 2019). "FLI1 expression did not correlate with tumor stage or differentiation, but was associated with patient survival, depending on tumor differentiation." (PMID 31231464, 2019). "Fli-1 also promotes angiogenesis, further contributing to tumor progression." (PMID 30741932, 2019). "Thus, Fli-1 inhibition blocks tumor growth in part by upregulating miR145, which is kept in check in untreated tumors by high levels of Fli-1." (PMID 30741932, 2019). "We then asked if FLI1 could serve as a marker for prognosis by determining if FLI1 IHC H-scores correlated with tumor differentiation, tumor stage (T1 to T4) or patient survival." (PMID 31231464, 2019). "Additionally, FLI1 was shown to be commonly hypermethylated and downregulated in colorectal adenomas and adenocarcinomas, further suggesting a possible tumor suppressor role in epithelial cells." (PMID 31231464, 2019). "Moreover, we demonstrated that ERG and FLI1 expression is downregulated in ECs within tumors by soluble factors enriched in the tumor microenvironment." (PMID 30500808, 2018). "In these cells, FLI1 promoted tumor metastasis by activating the miR-17-92 cluster family." (PMID 30537986, 2018). "Among these, we investigated whether soluble factors and hypoxia reduce the expression of ERG and FLI1, as aberrant soluble factor profiles and hypoxia are key characteristics of the tumor microenvironment." (PMID 30500808, 2018). "Thus, FLI1 drives tumor metastasis not only through the canonical oncoprotein pathway, but also by using epigenetic mechanisms mediated by its exonic circular RNA." (PMID 30537986, 2018). "In the tumor microenvironment, ERG and FLI1 can be downregulated via the mixture of cytokines from many sources such as infiltrating immune cells (e.g. neutrophils, macrophages, and NK cells), ECs, CAFs, and tumor parenchyma." (PMID 30500808, 2018). "Finally, we show that ERG and FLI1 expression is decreased in ECs within tumors, suggesting that EndMT is induced in the tumor microenvironment." (PMID 30500808, 2018). "Furthermore, we also show that ERG and FLI1 expression is downregulated in tumor tissues by soluble factors." (PMID 30500808, 2018). "We have discovered a novel epigenetic pathway by which FLI1 contributes to tumor metastasis." (PMID 30537986, 2018). "Since Fli-1 was originally identified as an oncogene involved in erythroleukemogenesis, this raises the question of how drug-mediated over-activation of this proto-oncogene can reverse its function to become a tumor suppressor." (PMID 28052010, 2017). "Restored expression of FLI-1 diminished miR-145-mediated suppression of tumor progression." (PMID 27304058, 2016). "Moreover, we restored the expression of FLI-1 in miR-145-transfected cells to explore the role of FLI-1 in miR-145-mediated tumor suppression." (PMID 27304058, 2016). "Since EWS/FLI1 expression is restricted to tumor cells, it represents an ideal therapeutic target." (PMID 26336820, 2015). "The role of FLI1 in tumor cell invasion was examined by the collagen-coated transwell assay." (PMID 26156017, 2015). "FLI1 oncoprotein activated the Rho GTPase pathway that is known to play a role in tumor metastasis." (PMID 26156017, 2015). "The primary tumor also shows a typical Fli-1 and INI-1 positive immunostaining phenotype." (PMID 26315812, 2015). "The tumor expressed strong Fli-1 positivity, an endothelial marker." (PMID 26106489, 2015). "Tumor cells stained diffusely positive for Fli-1, an endothelial cell marker." (PMID 26106489, 2015).
tumor (continued). "By injecting red fluorescent mammalian tumor cells into the Tg(fli1: EGFP) transgenic zebrafish, in which vascular endothelial cells are labeled by green fluorescent protein, both the process of tumor cell metastasis and changes in the vascular system can be clearly seen throughout the body." (PMID 26260237, 2015). "Therefore, although FLI1 expression can be detected in a tumor with an insertion in Fli1, expression is limited to a subset of cells in a specific region of the tumor." (PMID 25423036, 2014). "The suppression of EWS/FLI1 with nanocapsules is able to inhibit tumor growth in mice." (PMID 23329308, 2013). "We therefore analysed MigR1 control and Fli-1 tumour cells for the presence of 5′ Notch1 deletions." (PMID 23667468, 2013). "Therefore, we chose to analyse tissues from both MigR1 control and Fli-1 tumour cells for the presence of intracellular NOTCH1 protein by flow cytometry." (PMID 23667468, 2013). "Gene regulation imposed by EWS/FLI1 is felt to mediate important aspects of tumor phenotype." (PMID 23365673, 2013). "Therefore, in order to directly interrogate the impact of the EWS-FLI1 fusion gene on tumor formation, several laboratories have generated mouse models expressing an Ews-Fli1 transgene." (PMID 23036318, 2012). "A number of tumor related genes map in 11q distal region: EST1, CHK1, BARX2, OPCML, FLI-1, their role in tumor development and progression in JS is still unknown." (PMID 19267933, 2009). "However, given reports of tumor-intrinsic FLI1 promoting proliferation and invasion, some of this signal may represent adaptive responses to epigenetic stress." (PMID 41300765, 2025). "The results indicate that FLI1 may play a role in tumor progression, aggressiveness, and prognosis." (PMID 41300765, 2025). "The first strategy involves binding to receptors expressed specifically on the target cells; for example, antibody‒drug conjugates (ADCs) may improve the targeting of topoisomerase inhibitors (a kind of FLI-1 inhibitors) to tumour cells for increased effectiveness." (PMID 39107790, 2024). "To further examinate the role of miR-210-3p in mediating tumor cell behavior in zebrafish xenograft model, we injected approximately 100–150 SK-N-AS cells treated with EVs into the Duct of Cuvier of each embryo expressing the green fluorescent vascular marker Tg(fli1:EGFP) at 48 hpf." (PMID 37202777, 2023). "Moreover, circ-FLI1 silencing could restrain xenograft tumor growth of CC cells in nude mice in both the L-OHP treatment group and the vehicle group." (PMID 35647294, 2022). "Loss of nuclear FLI1 expression did not correlate with tumor stage or tumor differentiation." (PMID 31231464, 2019). "As a result, ERG and FLI1 expression was significantly decreased after a 4-hour conditioned media treatment by all three implanted tumors investigated, indicating that expression of these TFs is at least partially downregulated by soluble factors enriched in the tumor microenvironment." (PMID 30500808, 2018). "Therefore, FLI1+ cells observed adjacent to the ventricle could represent macrophages or other immune cells invading from the periphery into the tumor." (PMID 25423036, 2014). "Also, there may be tumor-suppressive molecules in addition to the EWS/Fli-1 mRNAs among the other contents of the MVs." (PMID 24124617, 2013). "Immunohistochemistry (IHC) showed positivity of the tumor cells for CD99 (cytoplasmic staining of moderate intensity in >50% of the tumor cells) and FLI-1 (nuclear staining of moderate intensity in >50% of the tumor cells)." (PMID 41230381, 2026). "The tumor cells exhibited an endothelial cell phenotype with diffuse strong positivity for CD34, CD31, ERG, and FLi-1, and diffuse and strong nuclear reactivity to TFE3." (PMID 39917171, 2025).
tumor (continued). "Immunohistochemically, the tumor cells in PHA demonstrate positivity for vimentin and the vascular lineage markers, including ERG, CD31, CD34, FLI-1, and factor VIII-related antigen." (PMID 41367857, 2025). "IHC of postoperative pathological sections confirmed high expression of ERG, FLI1, CD34 and PECAM1 in tumor cells." (PMID 41445863, 2025). "Tumor cells demonstrated strong diffuse membranous positivity for CD99 (approximately 95%) and focal nuclear expression of FLI-1 in about 30% of cells." (PMID 41589178, 2025). "In our patient's case, the tumor consisted of small round cells and was CD99+, BCOR+, FLI1+, TLE1−, and NKX2.2−." (PMID 40115314, 2025). "Tumour cells are thought to reside in a dynamic and metastable state fluctuating between ‘high’ or ‘low’ EWSR1::FLI1 expression." (PMID 40442778, 2025). "Afterwards they exploited an Albino Casper, TG(fli1:EGFP) strain, characterised by fluorescent vessels, to track the amount, size, and migratory routes of tumor cell foci for each embryo upon treatment with nutlin-3a and/or YK-4-279." (PMID 39200384, 2024). "The results of next-generation sequencing of tumor tissue showed that the EWSR1 and FLI1 genes were fused to form a new gene with transcriptional function." (PMID 38769118, 2024). "Since HSPA1B is negatively regulated by both UBASH3A and UBASH3B, its tumor suppressor activity is dependent upon balance between the level of these UBASH3 proteins, negatively and positively regulated by FLI1, respectively." (PMID 38461240, 2024). "In summary, we have deciphered a tumor-intrinsic mechanism of immune tolerance, wherein FLI1 promotes IFN-γ-induced Kyn production, thereby impairing T cell-mediated anti-tumor immunity." (PMID 38816360, 2024). "ARID1A serves as a critical interface between EWS::FLI1 and the BAF complex, with its condensate-forming ability essential for the aberrant gene expression that drives tumor growth." (PMID 39344201, 2024). "On the other hand, we found the cell-type-specific expression and function of FLI1 in BRCA based on single-cell analysis, especially showing cell-type-specific target genes and regulating intercellular communication in tumor microenvironment in BRCA." (PMID 38448802, 2024). "EWSR1–Friend leukemia integration one transcription factor (FLI1) acts as a potent tumor‐specific chimeric oncoprotein, and high EWSR1–FLI1 expression exponentially endows cancer cell proliferation." (PMID 39006762, 2024). "Overall, this review indicates that FLI-1 is a promising therapeutic target for SSc, LN,PAH and tumours, particularly for tumour treatment." (PMID 39107790, 2024). "ES is characterized by the uniform arrangement of small round bundles or diffuse tumor cells expressing CD99, FLI-1, Ki-67, CD38, and WT-1." (PMID 39139288, 2024). "FLI1 displayed lower expression in BRCA tissues than in normal tissues, which likely resulted from the decrease of endothelial cells in tumor tissues compared with normal tissues." (PMID 38448802, 2024). "Herein, we established a zebrafish xenograft metastasis model by transplanting DiI dye-labeled Caki-1 cells expressing shADAMTS1 or shCtrl into transgenic Tg (fli1: EGFP) zebrafish embryos, resulting in extensive dissemination of tumor cells." (PMID 39333870, 2024). "In our study, almost all neoplasms were positive for BCL2, CD99, CD56, FLI1, TLE1, MUC4, and PDGFR alpha." (PMID 39062853, 2024). "Although a tumor-specific target, EWSR1::FLI1-targeted therapy has yet to be developed, largely due to insufficient understanding of EWSR1::FLI1 upstream and downstream signaling, and the challenges in targeting transcription factors with small molecules." (PMID 36672331, 2023).
tumor (continued). "EWSR1::FLI1 repressed miR-708 expression to indirectly induce EYA3 transcription, and inhibited expression of the tumor suppressive miR-145, and other miRNAs including miR-22, miR29a, miR-100, miR-125b, miR-221/222 and miR-271 to modulate tumor growth." (PMID 36672331, 2023). "Here we demonstrate that the SIX1 homeoprotein, which enhances metastasis in most tumor types, suppresses ES metastasis by co-regulating EWS/FLI1 target genes." (PMID 37468459, 2023). "Here, the authors suggest that SIX1, which enhances metastasis in most tumour types, suppresses ES metastasis by co-regulating EWS/FLI1 target genes." (PMID 37468459, 2023). "The most common tumor-specific chimeric transcription factor, EWSR1-FLI1, consists of the Ewing sarcoma breakpoint region 1 protein (EWSR1) and an ETS family gene such as the Friend leukemia integration 1 transcription factor (FLI1)." (PMID 36497417, 2022). "Negative correlations between DNA methylation and gene expression of FLI1 have previously been reported in CRC lines, where gene silencing experiments have alluded to potential tumor suppressor functions." (PMID 36612042, 2022). "Immunohistochemically, tumor cells showed positivity for AE1/AE3, FLI-1, CD31 and ERG, and negativity for smooth muscle actin (SMA), desmin, CD 34, P40, CD1a, S100 P and CD163." (PMID 34514569, 2022). "EWS/FLI1 directly interacts with the SWI/SNF complex through ARID1A-L and regulates target gene expression, resulting in promoting tumor growth." (PMID 35954475, 2022). "The tumorigenicity experiment was carried out in nude mice, and sh-circ-FLI1-expressing HCT116 cells resulted in a delayed xenograft tumor growth regardless of L-OHP treatment, as evidenced by the decline of tumor volume and weight." (PMID 35647294, 2022). "Our co-culture experiment showed that FLI1 is involved in CCL3 secretion of TAMs and promotes tumor cell invasion." (PMID 33971970, 2021). "Immunohistochemical results exhibited that the CD31, CD34, F-VIII, FLI-1, and ERG were positive in tumor cells." (PMID 34032697, 2021). "In these cancers, miR-145 inhibits tumor proliferation by inhibiting the MYC and Friend leukemia virus integration 1 (FLI-1) genes." (PMID 34830370, 2021). "Postoperative pathology confirmed that the tumor was a small round-cell malignancy, and the tumor cells were positive for CD99, Friend leukemia virus integration 1 (FLI-1), and neuron-specific enolase (NSE), which was consistent with the diagnosis of a PNET." (PMID 33996888, 2021). "In contrast, CD31 is a more specific vascular tumor marker, so some scholars recommend immunohistochemical staining combined with CD31, ERG, FLI-1 as an important index for the diagnosis of EHE." (PMID 32812146, 2021). "Using the fish strain Tg(fli1:EGFP)(y1), which expresses EGFP throughout the vasculature under the control of the fli1 promoter, we examined the effects of JHH6 on tumor neo-angiogenesis." (PMID 34451900, 2021). "The inverse relationship between marinobufagenin and Fli1 opens new possibilities in the treatment of cancer; as Fli1 is a proto-oncogene, a hypothesis on the suppression of Fli1 by cardiotonic steroids as a potential anti-tumor therapeutic strategy is discussed as well." (PMID 33669287, 2021). "Immunochemically, the tumor cells were positive for CD31, ERG, Fli1, D2–40 and vimentin in a strong and diffused manner." (PMID 33509230, 2021). "Next, we focused on the ligand-receptor interactions between TAMs and tumor cells in different TME phenotypes and discovered that aberrant expressions of six hub genes, including FLI1, are involved in this process." (PMID 33971970, 2021). "Immunochemically, the tumor cells were positive for CD31, ERG, Fli1, D2–40 and vimentin in a diffused manner." (PMID 33509230, 2021).
tumor (continued). "Immunohistochemical staining indicated that tumor cells were positive for CD31, CD34, ERG, PCK, FLi-1, TFE-3, and Ki67 (labeling index, 5–15%)." (PMID 33121478, 2020). "We believed that this integrative study substantially improved our understanding of the important role of FLI1 in tumour microenvironment in BRCA patients and established an approach that can easily be extended to other types of tumours in the future work." (PMID 32249526, 2020). "Immunohistochemically, the tumor cells are positive for vascular markers (e.g., CD31, CD34, FLI1, and ERG)." (PMID 32316685, 2020). "By immunohistochemistry, tumor cells were positive for CD31, CD34, ERG, PCK, FLi-1, TFE-3, and Ki-67 (labeling index range, 5–15%)." (PMID 33121478, 2020). "It was suggested that tumor-related genes such as NNMT, FLI1, GAS6, IncRNA CCAT1, PDCD1LG2, and CD274 are key regulators in tumor-like transformation under long-time exposure to P. gingivalis." (PMID 30671195, 2019). "The ADAM19, FLI1, and MSC genes were hypermethylated in tumor tissues in 59 (41.8%), 57 (40.4%), and 80 cases (56.7%), respectively." (PMID 31675985, 2019). "In the current study, we found that soluble factors enriched in tumor tissues are responsible for reduced expression of ERG and FLI1." (PMID 30500808, 2018). "Thus, FLI1 may function as a tumor enhancer or promoter in solid tumors." (PMID 30537986, 2018). "Friend leukemia virus integration 1 (FLI1), an ETS transcription factor family member, acts as an oncogenic driver in hematological malignancies and promotes tumor growth in solid tumors." (PMID 30537986, 2018). "As FECR1 binds to the FLI1 promoter, we examined the cellular distribution of FECR1 in MDA-MB231 tumor cells." (PMID 30537986, 2018). "With the facilitation of bioinformatics analyses and validation, we identified some tumor-related genes, such as NNMT, FLI1, GAS6, lncRNA CCAT1, PDCD1LG2, and CD274, as the key regulators in the present tumor-like transformation model." (PMID 28286742, 2017). "The EWS/FLI-1 fusion product promotes tumor angiogenesis by upregulating VEGF-A expression, and in our study, Fli-1 knockdown attenuated the expression of Ki-67, VEGF, and cyclin D1 proteins." (PMID 28418872, 2017). "Overall, Ewing sarcoma EWS/FLI1 and MCP-1 expression promotes tumor development through immunosuppressive macrophage and M2-like osteoclast activation." (PMID 28536380, 2016). "For example, in PRAD, the most commonly found tumor subgroup has gene fusions involving members of the E26 transformation-specific (ETS) family of TFs, such as ERG, ETV1, ETV4, and FLI1." (PMID 27833659, 2016). "VEGF is involved in tumor angiogenesis and metastasis and is also upregulated by EWS/FLI1 and by tumor macrophages expressing IL-1 and MCP-1." (PMID 28536380, 2016). "Anti-FLI-1 compounds have demonstrated strong anti-leukemic activity in a mouse model that over-expresses FLI-1, making it possible to target FLI-1 as an anti-tumor treatment." (PMID 27304058, 2016). "Hence, the prevalent hypothesis states that EWS/FLI1 is the major genetic mutation that is necessary for development and maintenance of the tumor although it might not be sufficient." (PMID 26336820, 2015). "Immunohistochemical examination indicates that the tumor cells were diffusely positive for Factor VIII, Fli-1, CDK4, INI-1, MDM2, vimentin, focally positive for AE1/AE3, CD31 and negative for actin-sm, CD34, desmin, myoD1 and S-100." (PMID 26315812, 2015). "In the current case, immunohistochemical examination shows that the tumor cells were diffusely positive for endothelia cell markers Factor VIII and Fli-1 and focally positive for CD31." (PMID 26315812, 2015). "GSEA revealed that the Ewing family tumor gene signature and the various EWS/FLI1 target signatures are all enriched in genes with high binding of H3K27Ac in the enhancer region." (PMID 26337082, 2015).